APOE (apolipoprotein E)
Diseases named in the same sentence as APOE in open-access papers (continued):
Sharing a sentence is not in itself a finding about the gene and the disease.
atherosclerosis (continued). "Another study also demonstrated that the alkaline-extracted C. militaris polysaccharide CM3II (∼19.1 kDa), which consisted of →4)-β-D-Manp(1→6)-α-D-Manp(1→6)-β-D-Manp(1→ glycosyls, can attenuate atherosclerosis in apoE(-/-) mice." (PMID 34966782, 2021). "It is known that MMP-2 plays a role in promoting atherosclerosis, since atherogenesis is reduced in MMP-2-deficient ApoE−/− mice." (PMID 34797846, 2021). "Chondroitin sulfate, as a common drug for the treatment of OA, can reduce atherosclerosis in ApoE knockout mice." (PMID 34949204, 2021). "Additionally, it could be shown that PCSK9 aggravates atherosclerosis in apolipoprotein-E deficient mice, which was associated with an increased expression of inflammatory cytokines such as TNF-α, IL-1β, IL-10, MCP-1, and IL-8 to directly facilitate the process of inflammation." (PMID 34884827, 2021). "It was reported that LIGHT enhanced proliferating Ly6Chigh MC and increased atherosclerosis lesion size in ApoE-/-Irs2+/-HL-/- mice." (PMID 34987524, 2021). "In support of this notion, it is known that ApoE is an important modulator of atherosclerosis as it reduces cholesterol accumulation in vessels, and spontaneous hyperlipidemia and atherosclerosis have been observed in mice lacking ApoE." (PMID 34721384, 2021). "Supplementation of APH significantly attenuates atherosclerosis in ApoE−/− mice, exerting a lipid-lowering activity." (PMID 34206655, 2021). "S100/calgranulin, a pro-inflammatory protein, promotes the development of atherosclerosis with excessive cholesterol accumulation in atherosclerotic lesions in apoE-null mice." (PMID 34388961, 2021). "The vaccine was produced by sonicating P. gingivalis through heating, and a total of 32 male APOE-/-mice (8-week old) were subjected Western diet for 8 weeks, in order to induce atherosclerosis in a physiological manner." (PMID 33976982, 2021). "In apolipoprotein E (Apoe)-KO mice, a mouse model of atherosclerosis, TRPA1 channel activation with AITC was found to suppress atherosclerotic progression." (PMID 34064835, 2021). "Studies have also shown that Ang II infusion stimulates the progression of atherosclerosis in ApoE–/–mice." (PMID 34026753, 2021). "During the onset of atherosclerosis in ApoE-/- mice, macrophages, T cells, and dendritic cells were recruited into the adventitia and PVAT, in a manner influenced by age." (PMID 34456867, 2021). "ApoE-/- mice develop HL similar as that in humans and are an ideal model for atherosclerosis research." (PMID 34987524, 2021). "Supplementation of probiotic L. mucosae A1 exhibited effectiveness in the treatment of hyperlipidemia and atherosclerosis and improved gut microbiota dysbiosis, including increased richness and diversity in ApoE -/- mice on a Western diet." (PMID 34445037, 2021). "ApoE deficient mice received ERK1/2 inhibitor (U0126) treatment, followed by determination of atherosclerosis, calcification and miR-126-3p production." (PMID 33391525, 2021). "As disease progressed in the APOE ε4 genotype, brains were characterized by decreases in metabolites responsible for reducing atherosclerosis and the TCA cycle and oxidative phosphorylation." (PMID 35265943, 2021). "Liraglutide, a type of GLP1 receptor agonist, can inhibit the atherosclerosis of apoE mice and suppress the cellular behaviors of VSMCs induced by AngII." (PMID 34666623, 2021).
atherosclerosis (continued). "Dyslipidemia is a major initiator of atherosclerosis, and ApoE is particularly important to maintain the normal metabolism of lipoprotein." (PMID 34276559, 2021). "In summary, for the first time, we demonstrate that daily oral administration of 3‐HB once can attenuate atherosclerosis in apoE−/− mice." (PMID 33977048, 2021). "First, a model of atherosclerosis had been established on ApoE−/− mice following a WD, and then, the model mice were treated with PBMT for 10 weeks." (PMID 33951300, 2021). "Bearing in mind that the ApoE−/− mouse model has been widely used in atherosclerosis research, we utilized these mice as positive controls." (PMID 34440804, 2021). "To assess the impact of Siglec-E expression on atherosclerosis development, we generated apoE−/− mice with Siglec-E gene deletion (apoE−/−/SE−/− mice) for in vivo studies." (PMID 33397354, 2021). "VEGF C, PDGF A chain and APOE genes are strictly correlated in the pathogenesis of atherosclerosis, and their modulation by OL-HDF would suggest an anti-atherogenic effect of this treatment." (PMID 33761122, 2021). "Studies have demonstrated that angiotensin (Ang) II accelerates the development of atherosclerosis in apoE–/– mice." (PMID 33937238, 2021). "Here, we made an atherosclerosis with HHcy mice model by ApoE knockout mice and feeding Pagien diet and drinking L‐methionine water." (PMID 33675119, 2021). "Knockout of IKKε prevented significant atherosclerosis lesions in mouse aortas from both wild-type and ApoE knockout mice that were fed a high-fat diet." (PMID 33628362, 2021). "Functions of ApoE involve cholesterol efflux, more specifically involved in cholesterol-loaded macrophage foam cells, and other atherosclerosis-relevant cells." (PMID 35011591, 2021). "This study assessed the effect of a 10% (w/w) anchovy waste protein hydrolysate (APH) diet for 12 weeks in reducing atherosclerosis in ApoE−/− mice, through histological and immunohistochemical methods." (PMID 34206655, 2021). "Endothelial cell-specific GR deletion results in more severe atherosclerosis and increased recruitment of macrophages in an ApoE−/− model of atherosclerosis." (PMID 34299240, 2021). "The deficiency of glutathione peroxidase (Gpx)-1 exacerbates atherosclerosis and loss of heme oxygenase-1 (HO-1) accelerates the development of atherosclerosis and vascular remodeling in ApoE‒/‒ mice." (PMID 34439492, 2021). "Previous studies have shown that treatment with salidroside or Melatonin decreases atherosclerosis plaque formation in the aorta of HFD-fed ApoE−/− mice via inhibiting endothelial cell pyroptosis." (PMID 33967800, 2021). "CX3CR1−/− apoE−/− mouse model showed an impaired survival of Ly6Clow monocytes and enhanced atherosclerosis." (PMID 34572399, 2021). "In this study, the influence of 10% (w/w) anchovy protein hydrolysate supplementation for 12 weeks in attenuating atherosclerotic plaque formation was assessed in ApoE−/− mice, as an atherosclerosis-prone mouse model." (PMID 34206655, 2021). "It was known that HCD accelerated the development of atherosclerosis, as compared with chow diet in ApoE−/− mice." (PMID 34836239, 2021).
atherosclerosis (continued). "In this study, we exhibited that MCC950 has the effect of anti-atherosclerosis by inhibiting plaque formation in the aortas of apoE−/− mice with high fat diet for 12 weeks." (PMID 34588488, 2021). "Our results showed that severe atherosclerosis was successfully induced in our model, while 12 weeks of HT-AC treatment decreased the lipid deposition and plaque formation in ApoE−/− mice fed with HFD." (PMID 33967800, 2021). "To evaluate the impact of DIZE on the development of atherosclerosis, we treated apoE−/− mice fed a high-fat diet with DIZE (30 mg per kg of body weight per day) for 16 weeks." (PMID 34070749, 2021). "Herein, the effects and molecular mechanisms involving ferulic acid (FA) was examined in atherosclerosis using the ApoE-knockout (ApoE-∕-, c57BL/6 background) mouse model." (PMID 33841148, 2021). "Recently, the link of TMAO-induced atherosclerosis with bile acid metabolism was studied in apoE−/− mice on TMAO-containing diet." (PMID 33072766, 2020). "On the other hand, this peptide was proven to retard atherosclerosis in apoE KO mice by improving the anti-inflammatory properties and the cholesterol efflux capacity of HDL." (PMID 32485898, 2020). "Together, these data suggest that knockout of LMP10 attenuates diet-induced atherosclerosis possibly through inhibition of macrophage infiltration and death in ApoE ko mice." (PMID 33195259, 2020). "Development of apoE-/- mice was an important step in the study of atherosclerosis and helped to establish some important disease mechanisms." (PMID 32428130, 2020). "APOE*3-Leiden transplanted bone marrow was less effective in reducing atherosclerosis, as compared with bone marrow cells expressing wildtype murine APOE." (PMID 32849290, 2020). "We investigated the effect of such lipid-lowering interventions on atherosclerosis in APOE*3-Leiden.CETP mice, a well-established model for hyperlipidemia." (PMID 31843957, 2020). "Here in this study, we explored this issue in a mouse atherosclerosis model, the apolipoprotein E-knockout mice (Apoe-/-) fed on an atherogenic diet." (PMID 32258175, 2020). "MiR-520a-3p inhibition elevated the expression levels of α-SMA and collagen, which were inhibited in lesions in apoE-/- mice with atherosclerosis." (PMID 33768113, 2020). "In this study, we tested alirocumab and/or evinacumab on top of atorvastatin as high-intensive lipid-lowering strategy to evaluate their effect on regression of pre-existent atherosclerosis in APOE*3-Leiden.CETP mice." (PMID 31843957, 2020). "Abatacept also reduced the expression of this adhesion molecule in the aortic lysates of ApoE−/− mice that were subjected to hyperhomocysteinaemia-accelerated atherosclerosis by limiting the expression of inflammatory cytokines." (PMID 32872393, 2020). "Even when the ApoE-/- model was integrated, these mice showed less atherosclerosis development and increased survival compared to wild-type and either the individual FABP-deficient counterparts." (PMID 33105856, 2020). "•These data provide information on the transcriptional effects on whole aorta after treatment with alpha 7 nicotinic acetylcholine receptor (α7nAChR) agonist AZ6983 in the atherosclerosis-prone ApoE-/- mouse." (PMID 32258279, 2020). "To assess if there was an association between the differential immune response to the self-peptides observed and atherosclerosis, we examined atherosclerosis in female compared to male apoE–/– mice fed high fat diet for 12 weeks." (PMID 32373127, 2020).
atherosclerosis (continued). "Apolipoprotein E (ApoE), a component of major lipoprotein classes, not only plays a vital role in the development of atherosclerosis in humans but participates in the modulation of immune response and inflammation as well." (PMID 33297350, 2020). "Pathway enrichment analysis via Enrichr identified apoptosis-related network (p = 2e-3), statin pathway (p = 9e-3), and ApoE-related inflammation and atherosclerosis (p = 0.04)." (PMID 33137096, 2020). "We also know that endogenous E2 is highly protective in the ApoE−/− mouse model as ovariectomy increases atherosclerosis in young mice." (PMID 32630298, 2020). "In fact, along with developing early-onset atherosclerosis, ApoE−/− mice develop emphysema due to the impaired development of lung alveoli." (PMID 32331221, 2020). "DPP-IV inhibitor, teneligliptin, reduces atherosclerosis progression in apolipoprotein E (ApoE) knockout mice by alleviating inflammation and oxidative stress in both the vasculature and PVAT." (PMID 33050331, 2020). "In atherosclerosis, increased interactions between mesenchymal-like cells and immune cells have been reported in the ApoE−/− mouse model." (PMID 32630148, 2020). "The role that macrophages play in response to nicotine in atherosclerosis can also be observed in ApoE−/− mice." (PMID 32331221, 2020). "In our previous study, Cyp27a1 deficient mice on ApoE−/− background, (DKO mice), fed with WD developed 10-fold less atherosclerosis than their ApoE KO littermates." (PMID 33193099, 2020). "Increasing evidence has demonstrated that nicotine increases atherosclerosis in ApoE–/– mice through the activation of α7nAChRs in mast cells, supporting its pro-inflammatory effects." (PMID 33424644, 2020). "Here we investigated the effect of ribose-cysteine supplementation on GSH-based antioxidant activity and atherosclerosis development in the apoE-/- mouse." (PMID 32084149, 2020). "To determine the role of CD147 in atherosclerosis development, we first assessed its expression in the aorta of Western diet-fed ApoE–/– mice, a commonly used animal model of atherosclerosis." (PMID 33490072, 2020). "This controversy of effect of E2 on calcification also exists in the apolipoprotein E-null (ApoE−/−) mouse model of atherosclerosis." (PMID 32630298, 2020). "For example, the T cell-specific overexpression of CTLA4 reduced atherosclerosis in ApoE−/− mice and limited the numbers of CD4+ T cells and macrophages in the plaque and decreased systemic T cell activation." (PMID 32872393, 2020). "In ApoE−/− mice model of atherosclerosis, the hypercholesterolemia led to early renal dysfunction that can progress into chronic KD38." (PMID 33122777, 2020). "In this study, we provided evidences on the anti-atherosclerosis effect of honokiol with an ApoE-/- mouse model and compare its effect with statins for the first time." (PMID 32365054, 2020). "As critical examples, when compared with control animals, TNF-α and Apo E double-knockout mice have less atherosclerosis and reduced endothelial adhesion; an effect replicated in ApoE mice treated with agents that reduce TNF-α activity." (PMID 33025148, 2020). "There are few infarct studies in ApoE*3-Leiden mice to date, even though these mice appear to be a suitable animal model of atherosclerosis." (PMID 33258000, 2020). "A study using ApoE−/− mice reported that the administration of FGF21 alleviated atherosclerosis by ameliorating Fas-mediated apoptosis." (PMID 32957703, 2020). "Taken together, we chose the high-fat diet to induce atherosclerosis in ApoE−/− mouse model in this study." (PMID 32472055, 2020).
atherosclerosis (continued). "This study aims to investigate the effects of kefir peptides on high-fat diet (HFD)-induced atherosclerosis in apolipoprotein E knockout (ApoE−/−) mice." (PMID 32472055, 2020). "ApoE is a protein responsible for fat metabolism and ApoE KO mice represent a model for atherosclerosis in humans." (PMID 33022979, 2020). "Silencing of miR-520a-3p by specific antagomiRNA reduced the plaque area of lesions in apoE-/- mice with atherosclerosis." (PMID 33768113, 2020). "Our results were in accordance with the previous reports: the lymphatic vessels in mouse heart atrium increased in model group, while AMY reversed the proliferation of heart lymphatic vessels in ApoE−/− atherosclerosis mouse model." (PMID 33192531, 2020). "A. muciniphila is a kind of mucin-producing bacteria that can repair damage to the intestinal barrier in atherosclerosis models of ApoE−/− mice." (PMID 31992206, 2020). "Rapamycin attenuated atherosclerosis induced by dietary cholesterol in ApoE−/− mice via upregulating SIRT1 and inactivating YAP." (PMID 32081881, 2020). "Our study presents the course of ETAR expression in early atherosclerosis of ApoE−/− mice and in advanced atherosclerotic plaques from humans by combining quantitative molecular biology as well as molecular imaging techniques." (PMID 33255872, 2020). "The findings demonstrate that both high and low-dose BBR can improve serum lipid and systemic inflammation levels, and alleviate atherosclerosis induced by high-fat diet in ApoE–/– mice." (PMID 32231564, 2020). "The level of Gal-3 was demonstrated to develop in human atherosclerosis plaque and some animal models, especially hypercholesterolemic rabbits and Apolipoprotein-E knockout (ApoE−/−) mice with vascular stenosis." (PMID 32149158, 2020). "In atherosclerotic plaques from apoE−/− atherosclerosis mouse model and from human coronary arteries, this lncRNA was found to be downregulated." (PMID 32197550, 2020). "In apoE-/- mice, atherosclerosis development is initiated spontaneously, even when animals are kept on a regular rodent diet, but can be accelerated by applying cholesterol- and fat-enriched Western type diet." (PMID 32428130, 2020). "ApoE-/- mice show a marked depletion in GSH in the aortic arch before the onset of atherosclerosis due to reduced GSH synthesis." (PMID 32084149, 2020). "In the vascular wall, oxidative stress is counteracted by several antioxidant enzyme systems including SOD1 and CAT; indeed, in ApoE KO mice, the overexpression of both genes reduced atherosclerosis." (PMID 32824091, 2020). "ApoE KO mice develop accelerated atherosclerosis, especially when fed with pro-atherogenic western diet (WD), but the atherosclerotic phenotype of ApoE KO was unexpectedly abolished in DKO mice fed with WD." (PMID 33193099, 2020). "In another study, the effect of monocyte/macrophage-expression of APOE and APOE*3-Leiden was investigated by transplanting bone marrow into atherosclerosis-prone Apoe−/− mice." (PMID 32849290, 2020). "Hematoxylin and eosin (H&E), Masson and Oil Red O staining were used to evaluate the effects of NORAD-knockdown on atherosclerosis in ApoE−/− mice." (PMID 32267831, 2020). "Previous genetic studies of Gal-3 and atherosclerosis mainly focused on the comparison between Apolipoprotein-E/Gal-3 double knockout (ApoE−/−/gal-3−/−) mice and ApoE−/− mice." (PMID 32149158, 2020). "To better explore the impact of SVEP1 on atherosclerosis, we crossbred ApoE−/− mice with Svep1+/+ or Svep1+/− mice and hence generated atherosclerosis-prone mice with either normal (ApoE−/−Svep1+/+) or reduced (ApoE−/−Svep1+/−) wildtype Svep1 levels." (PMID 33185739, 2020).